IL6R (interleukin 6 receptor)
Diseases named in the same sentence as IL6R in open-access papers (continued):
Sharing a sentence is not in itself a finding about the gene and the disease.
type 1 diabetes (12 papers, 2013 to 2026). "We evaluated whether blockade of IL-6R with monoclonal antibody tocilizumab would slow loss of residual β cell function in newly diagnosed type 1 diabetes patients." (PMID 34747368, 2021). "A recent clinical study tested the effects of two different monoclonal antibodies (mAbs) (siltuximab, anti-IL6; tocilizumab, anti-IL6R) on the fate and function of T-cells in people with type 1 diabetes." (PMID 41959136, 2026). "We did not observe such robust evidence for co-localisation between IL2RA, IL6R, IL6ST or TYK2 eQTL and the risk of type 1 diabetes in other cell types or in spleen or pancreas." (PMID 39271518, 2024). "We found evidence for a shared causal variant between the risk of type 1 diabetes and whole-blood IL2RA (rs61839660, posterior probability 100%), IL6R (rs10908839, posterior probability 96.5%) and IL6ST gene expression (rs7731626, posterior probability 97.0%)." (PMID 39271518, 2024). "Among these genes, five (IL6R, RBPJ, SKAP2, SIRPG, UBASH3A) harbour a nearby type 1 diabetes-associated SNP." (PMID 37224769, 2023). "We performed short-term interventions in individuals with type 1 diabetes using anti–IL-6 (siltuximab) or anti–IL-6 receptor (IL-6R; tocilizumab) therapies and investigated the impact of this in vivo blockade on T cell fate and function." (PMID 36282595, 2022). "IL-6 receptor (IL-6R) signaling drives development of T cell populations important to type 1 diabetes pathogenesis." (PMID 34747368, 2021). "To study which specific blood immune cells or tissues mediate the association between IL2RA, IL6R, IL6ST and TYK2 expression and type 1 diabetes risk, we analysed their pairwise co-localisation with type 1 diabetes risk in spleen, pancreas and subsets of blood immune cells." (PMID 39271518, 2024). "Tocilizumab reduced T cell IL-6R signaling but did not modulate CD4+ T cell phenotypes or slow the loss of residual β cell function in newly diagnosed individuals with type 1 diabetes." (PMID 35563276, 2022). "Tocilizumab reduced T cell IL-6R signaling but did not modulate CD4+ T cell phenotypes or slow loss of residual β cell function in newly diagnosed individuals with type 1 diabetes." (PMID 34747368, 2021). "The OR (95% CI) of type 1 diabetes per 1-SD increase in the genetically proxied gene expression of IL2RA, IL6R and IL6ST were 0.22 (0.17, 0.27), 1.98 (1.48, 2.65) and 1.90 (1.45, 2.48), respectively." (PMID 39271518, 2024). "Furthermore, our co-localisation results suggest that associations between whole-blood IL2RA and IL6R expression and the risk of type 1 diabetes are unlikely to be caused by LD with a genetic variant that primarily influences the reading of other genes in the vicinity of IL2RA or IL6R loci." (PMID 39271518, 2024). "To address this gap in knowledge, we used samples from 2 independent mechanistic clinical studies in patients with established type 1 diabetes (T1D) to compare the effect of anti–IL-6 (siltuximab) and anti–IL-6R (tocilizumab) therapies on T cell fate and function." (PMID 36282595, 2022). "Furthermore, our Mendelian randomisation estimates represent the influence of small changes in IL2RA, IL6R and TYK2 expression during the entire life course before the diagnosis of type 1 diabetes." (PMID 39271518, 2024). "Interestingly, a recent integrative analysis of genetic association, functional genomics data and protein–protein networks identified DGKQ as a potential novel type 1 diabetes therapeutic gene target along with other novel and known targets, e.g., IL2RA, IL6ST, IL6R and TYK2." (PMID 35142878, 2022). "However, since IL6ST expression in CD4+ and CD8+ naive or central memory T cells co-localised with type 1 diabetes and IL6R expression did not, it is tempting to speculate that trans-signalling might be more important than classic IL-6 signalling in the pathogenesis of type 1 diabetes." (PMID 39271518, 2024).
abdominal aortic aneurysm (11 papers, 2013 to 2024). Enlargement and ballooning of the vessel that supplies arterial blood to the abdomen, pelvis and legs. "The present study shows that the single nucleotide polymorphisms (SNPs) of the genes CDKN2BAS rs10757278, LPA rs3798220, SORT1 rs599839, DAB2IP rs7025486, and IL6R rs2228145 are associated with the development of abdominal aortic aneurysms (AAA) in a study population." (PMID 37893562, 2023). "Similarly, IL6R expression in multiple tissues including artery, colon, and esophagus was associated with increased risk of coronary revascularization, coronary atherosclerosis, and abdominal aortic aneurysm (AAA), but lower risk of lower respiratory diseases and atopic dermatitis." (PMID 39563277, 2024). "The Asp358Ala variant (rs2228145; A>C) in the IL (interleukin)-6 receptor (IL6R) gene has been implicated in the development of abdominal aortic aneurysms (AAAs), but its effect on AAA growth over time is not known." (PMID 30657332, 2019).
allergic disease (11 papers, 2014 to 2025). An immune response that occurs following re-exposure to an innocuous antigen, and that requires the presence of existing antibodies against that antigen. "The results demonstrated a significant association of TNFAIP3, IL1RL2, IL1R1, IL6R, KYNU, and ITPKA with allergic diseases in both cohorts, further supporting the reliability of the potential drug targets identified in this study." (PMID 38573314, 2024). "Though best known in allergy and anaphylaxis, the TME mast cells highly express immunosuppressive IL6R and ferroptosis-related signatures including PEBP1 and NCOA4." (PMID 36148946, 2022). "We found that IL-6 and IL-6R existed in cells around the inflammatory tissues of RA patients, inferring that IL-6 was correlated with ARD joints, and played an essential role in its pathogenesis, the effect of which is evident in allergic reaction-related parts." (PMID 25097512, 2014).
ischemic stroke (11 papers, 2016 to 2026). A stroke disorder caused by obstruction of blood flow to the brain, due to thrombotic (local blood clot formation) or embolic (due to a blood clot or other material traveling from another site) event. "Results from Mendelian randomization studies indicate a causal association between the IL6R, AF and ischemic stroke and that the increased risk of ischemic stroke associated with the IL6R is accounted for by AF." (PMID 34372806, 2021). "IL-6 is the main driver of the production of the pro-inflammatory cytokine of CRP production in the liver, which is associated with an increased risk of ischemic stroke and is involved in the process of ischemic brain injury by binding to IL-6R to initiate intracellular signaling." (PMID 38104193, 2023). "To explore this difference, we measured circulating soluble IL-6R (sIL-6R) levels in mice and patients with ischemic stroke." (PMID 42146493, 2026). "Therefore, we conducted this multicenter prospective cohort study based on our previous community-based cross-sectional survey and found that IL6R rs4845625TT significantly increased ischemic stroke and composite vascular events." (PMID 38827573, 2024). "The membrane-bound IL-6R is composed of two subunits: the IL-6R-α chain (to which IL-6 binds) and the assisting transmembrane signaling subunit, glycoprotein 130 (gp130), which is the intra-cellular signal transducer and abundantly expressed during ischemic stroke." (PMID 34691061, 2021).
atopic dermatitis (10 papers, 2019 to 2025). "Descriptions of monogenic IEI are also supported by GWAS studies that have identified IL-6R polymorphisms associated with atopic dermatitis, elevated IgE, and asthma." (PMID 35572516, 2022). "IL6R deficiency – Two patients with atopic dermatitis, recurrent skin and lung infections, sinopulmonary infections, and elevated serum IgE, were described as having a homozygous variant in IL6R." (PMID 35185921, 2022). "One GWAS previously reported an association between elevated soluble IL-6R levels resulting from an SNP in IL-6R and atopic dermatitis." (PMID 31276585, 2019). "Here, we focus on the soluble form of IL-6R (sIL-6R) cleaved from membrane-bound IL-6R, which is associated with the enhancement in the proinflammatory responses in skin, including psoriasis atopic dermatitis and barrier repair following injury, triggered by the signal “alarmin”." (PMID 41303453, 2025). "Indeed, the inhibition of IL-6R/sIL-6R through the use of the mAb tocilizumab at the dose of 8 mg/kg of body weight every 4 weeks was shown to decrease the clinical signs of atopic dermatitis." (PMID 38541700, 2024). "Surprisingly, neither COL6A3, PPCS, nor IL6R levels were causally associated with increased risk of coronary atherosclerosis in this cohort, although higher levels of circulating IL6 receptor were causally associated with increased risk of atopic dermatitis." (PMID 38989470, 2024).
Cachexia (10 papers, 2011 to 2025). Severe weight loss, wasting of muscle, loss of appetite, and general debility related to a chronic disease. "We have recently reported that IL-6 receptor (IL-6r) antibody administration to cachectic ApcMin/+ mice attenuates further progression of cachexia, and was associated with suppressed muscle protein degradation." (PMID 22769563, 2012). "Individuals with congenital IL-6R deficiency experience recurrent bacterial infections, prompting concerns among clinical experts that IL-6R inhibition may compromise the body’s ability to resist pathogens, leading to severe infections, which is a high risk for patients with cachexia." (PMID 39703501, 2024). "Together, these results indicate that the IL-6Rα on AP neurons, especially that on Gfral+ neurons, is a critical mediator of IL-6 function in the development of cancer cachexia in the C26 model." (PMID 38824130, 2024). "Studies in rodents have elucidated a close association between the IL-6/IL-6R/STAT-3 cascade and muscle degradation during cachexia progression." (PMID 39703501, 2024). "Physiological levels (those observed in KPC cachexia) of IL6R elicited adipocyte lipolysis, while physiological levels of IL-6 did not, suggesting that IL6R is limiting for signaling in fat and thus must be supplied by trans-signaling." (PMID 33851955, 2021). "Given the low abundance of IL-6R on muscle cells, it is possible that, during cachexia, autophagy induced by IL-6 trans-signaling plays a dominant role." (PMID 28515477, 2017). "Further, alterations in the expression of these proteins can be suppressed by the administration of an IL-6r antibody after the initiation of cachexia." (PMID 22769563, 2012). "While our current study reports that two weeks of elevated circulating IL-6 was not sufficient to reduce muscle mitochondrial content, the IL-6r antibody treatment after the initiation of cachexia was able to significantly attenuate the loss of mitochondria." (PMID 22769563, 2012). "IL-6r antibody administration from 16 to 18 weeks of age attenuated the progression of cachexia." (PMID 21949739, 2011). "These facts support the finding that the IL-6r antibody treatment was diminishing the rate of cachexia development, but was not reversing the process." (PMID 21949739, 2011). "ApcMin/+ control mice not treated with the IL-6r antibody increased total protein degradation by 2.5 fold (P<0.001) during the progression of cachexia, which involved ATP dependent and independent mechanisms of degradation." (PMID 21949739, 2011). "Furthermore, many factors upstream, downstream, and independent of IL-6 and IL6R clearly modulate the development and severity of cachexia in preclinical models." (PMID 33851955, 2021). "However, muscle protein ubiquitination and proteasomal subunit expression in ApcMin/+ mice treated with the IL-6r antibody remained elevated when compared to non-cachectic muscle, which was expected since the treated mice had already initiated cachexia." (PMID 21949739, 2011).
gastric cancer (10 papers, 2014 to 2024). A primary or metastatic malignant neoplasm involving the stomach. "The prognostic role of the functional IL-6 (promoter) rs1800795 and the IL-6R (receptor) rs8192284 single nucleotide polymorphisms (SNP) was studied in patients with advanced gastric cancer treated with palliative chemotherapy." (PMID 24886605, 2014). "MiR-23a was revealed to down regulate the interleukin-6 receptor, boosting the development of gastric cancer cells." (PMID 38195397, 2024). "In contrast, the IL-6R 48892 C/C genotype was reported to have an adverse prognostic effect in patients with advanced gastric cancer." (PMID 38469154, 2023). "For the molecular mechanisms, CDDP alone increased the cancer stem cell (CSC)-like properties in gastric cancer cells via activating the interleukin-6 (IL-6)/IL-6 receptor (IL-6R)/signal transducer and activator of transcription 3 (STAT3) signaling." (PMID 27824145, 2016). "The IVW method revealed that the interleukin 6 receptor was inversely correlated with gastric cancer progression (OR = 0.86, 95% CI = 0.74–0.99, P = .03), whereas fatty acid-binding protein 4 was found to elevate the risk (OR = 1.21, 95% CI = 1.05–1.39, P = .03)." (PMID 38306562, 2024). "Our research suggests that the interleukin 6 receptor potentially mitigates, while fatty acid-binding protein 4 may contribute to the pathogenesis of gastric cancer (GC)." (PMID 38306562, 2024). "Our results identified STING as a prognostic factor for GC, and for the first time showed that knocking-down STING and STING activation by 2'3'-c-GAMP both promote TAMs differentiating into pro-inflammatory subtype and induce apoptosis of gastric cancer cells by activating IL6R-JAK-IL24 pathway." (PMID 31903134, 2020). "Chronic ROS and oxidative stress can consequently suppress the antioxidant system and induce several signaling pathways such as interleukin-6 receptor (IL-6R)/gp130/STAT3 signaling pathway, leading to radiotherapy-resistant gastric cancer." (PMID 38053578, 2023).
psoriasis (10 papers, 2014 to 2025). An autoimmune condition characterized by red, well-delineated plaques with silvery scales that are usually on the extensor surfaces and scalp. "Taken together, blockade of IL-6 signaling with an anti-IL-6R antibody is a potential therapeutic approach to resolve psoriasis-like dermatitis caused by inhibition of PD-1." (PMID 33060784, 2020). "As expected, a murine model of IMQ-induced psoriasis-like dermatitis enhanced via PD-1 deficiency was significantly improved by anti-IL-6R blocking antibody." (PMID 33060784, 2020). "Tofacitinib and other Janus kinase inhibitors (targeting, among the others, also the IL-6R signaling pathway) are gaining significant attention as therapeutic options in psoriasis, but their efficacy in PP is still unclear." (PMID 25126586, 2014). "Collectively, this treatment strategy comprised of selective blockade of IL-6 signal with anti-IL-6R blocking antibody could be effective and ideal for treating PD-1 signal blockade-induced psoriasis-like dermatitis." (PMID 33060784, 2020). "Therefore, we employed blockade of IL-6 signaling using an anti-IL-6R blocking antibody (MR16-1) in order to assess the effects on IMQ-induced psoriasis-like dermatitis." (PMID 33060784, 2020). "Furthermore, we employed blockade of IL-17A signaling using an anti-IL-17A neutralizing monoclonal antibody in order to compare the effect with anti-IL-6R antibody on IMQ-induced psoriasis-like dermatitis in PD-1−/− mice." (PMID 33060784, 2020). "In addition, in psoriasis patients, IL-6R-expressing Tregs have been previously shown to be recruited to the inflamed skin, where they co-localise with the pathogenic IL-17 producing Th17 effector cells." (PMID 28284938, 2017). "Therefore, blocking this trans-signaling process with anti-IL-6R antibody might decrease the inflammation seen during PD-1 signal inhibition-provoked psoriasis-like dermatitis by impairing the promotion of CD8 T cells." (PMID 33060784, 2020). "While IL-6R activates the Akt and MAPK pathways in dermal fibroblasts, STAT3 is known to be activated in keratinocytes, specifically at the wound edge, during healing as well as during skin pathologies such as psoriasis." (PMID 31073533, 2019). "Taken together, the deletion of IL-6Rα in the myelomonocytic compartment did not affect the development of IMQ-induced psoriasis-like skin disease." (PMID 26999594, 2016). "So, the inflammatory cell invasion to the skin accompanied by the clinical signs of psoriasis was not at all reduced when the IL-6Rα in myelomonocytic cells was deleted." (PMID 26999594, 2016). "In this study, we deleted the IL-6Rα specifically in the myelomonocytic cells, expecting these mice to develop a milder form of disease–in order to further investigate the role of IL-6 in the context of IMQ-induced psoriasis-like skin disease." (PMID 26999594, 2016). "Strikingly, in recent reports, IL-6/IL6R-mediated STAT3 activation in keratinocytes, rather than in immune cells, was responsible for the development of the psoriatic phenotype in a mouse model, highlighting the localized production and activity of IL-6 as being fundamental in psoriasis development." (PMID 38672088, 2024).
neuroblastoma (9 papers, 2010 to 2024). Neuroblastoma (NB) is the most common solid, extracranial childhood tumor. "In the scope of the study, vehicle control, DX and NP doses were applied individually and in combination to SH-SY5Y neuroblastoma cells, and IL-6, IL-6-R, Jak2, and Stat3 gene expressions were determined at the end of 48 hours." (PMID 39356934, 2024). "This is similar to data for neuroblastoma showing expression of IL6R/IL6R mRNA in most of the cell lines studied." (PMID 26215971, 2015). "Subsequently, we examined IL6R expression in six neuroblastoma cell lines in our laboratory and found that IL6R was expressed in most NB cell lines except SH-SY5Y cell." (PMID 34790130, 2021). "Biochemical evidence demonstrates that in primary cortical neurons and SH-SY5Y neuroblastoma cells, IL-6 cytokine family members, OSM and IL-6 plus the soluble IL-6R (IL-6/R), prevent NMDA and glutamate-induced neuronal toxicity." (PMID 23226414, 2012).
osteoarthritis (9 papers, 2011 to 2025). A noninflammatory degenerative joint disease occurring chiefly in older persons, characterized by degeneration of the articular cartilage, hypertrophy of bone at the margins and changes in the synovial membrane. "It is shown that the activation of T cell homeostasis in osteoarthritis is mediated by IL6R." (PMID 40181977, 2025). "Taken together, hyperacute serum can be a promising blood separation product in degenerative joint diseases, which enhances cell proliferation, the production of COL1A1 and osteonectin, while decreasing the level of RANKL, IL-1β, IL-6Rα, IL-12, and TNF-α." (PMID 31382623, 2019). "We determined the interleukin 6 (IL-6), IL-6 receptor α (IL-6Rα), gp130, receptor activator of nuclear factor κB ligand (RANKL), matrix metalloproteinase 3 (MMP3), TIMP metallopeptidase inhibitor 1 (TIMP1), and Bcl-2 levels in RA and osteoarthritis (OA) serum and synovial fluid." (PMID 29755657, 2018).